CXCR4 (C-X-C motif chemokine receptor 4)
Diseases named in the same sentence as CXCR4 in open-access papers (continued):
Sharing a sentence is not in itself a finding about the gene and the disease.
colorectal cancer (continued). "High CXCR4 expression in colorectal cancer specimens was accompanied by a significantly diminished disease-free survival (HR = 2.68, 95% CI [1.41; 5.08], p = 0.0026)." (PMID 38791414, 2024). "Nevertheless, further studies and phase II/III trials are needed evaluating CXCR4 antagonists serving as potential new targeted therapies in colorectal cancer patients." (PMID 38791414, 2024). "Kim and others determined that isoimperatorin regulates NF in colorectal cancer cells and liver cancer cells, downregulating epithelial-mesenchymal transition via κB signaling and CXCR4 expression." (PMID 38915466, 2024). "Our recent study showed that A1, a novel fluorinated CXCR4 inhibitor, can effectively treat colorectal cancer (CRC) in vitro and in vivo." (PMID 39070795, 2024). "Activation of CXCL12/CXCR4 confers radioresistance of colorectal cancer cells by upregulating survivin expression." (PMID 38164179, 2024). "To test this possibility, we subcutaneously administered the same amount of T22‐GFP‐H6, in both soluble (IN) and MP versions, in a mouse model of CXCR4+ colorectal cancer." (PMID 38501900, 2024). "In summary, in this systematic review and meta-analysis, a significant negative influence on overall as well as disease-free survival was shown for the chemokine receptor CXCR4 in primary colorectal cancer patients." (PMID 38791414, 2024). "They analyzed the CXCR4 mRNA expression in colorectal carcinoma tissue from 48 patients using qRT-PCR and compared the expression level with the corresponding non-tumorous tissue." (PMID 38791414, 2024). "Nanostructured toxins for the selective destruction of drug-resistant human CXCR4(+) colorectal cancer stem cells." (PMID 37238692, 2023). "Recent studies have shown that CXCR4 inhibitors can enhance T cell and B cell infiltration and induce immune responses in pancreatic and colorectal cancers." (PMID 36308553, 2023). "EMT and miR-125b are both simultaneously upregulated in human colorectal carcinoma (CRC) cells when the CXCR4/CXCL12 axis is activated." (PMID 37375460, 2023). "Signaling through the CXC chemokine receptor 4 (CXCR4) expressed on colorectal cancer (CRC) cells has a pivotal role in tumor cell chemosensitivity." (PMID 36290780, 2022). "Recent PNAS study reported that CXCR4 inhibition in combination with blockade of the PD-1/PD-L1 induced T cell infiltration and anticancer responses in human pancreatic and colorectal cancers." (PMID 35174151, 2022). "MIF/CXCR4 signaling promotes neovascularization, migration, and invasion phenotypes in colorectal cancer, non-small cell lung cancer, and glioblastoma." (PMID 35715791, 2022). "For example, miR-146 inhibits CXCR4 expression, thus hindering the proliferation and migration of colorectal cancer cells." (PMID 35893797, 2022). "The high mortality rate of colorectal cancer (CRC) is associated with metastasis to the liver, which is related to an increased expression of the C-X-C chemokine receptor 4 (CXCR4)." (PMID 36428644, 2022). "In colorectal cancer, recruited CXCR4+ cells are predominantly immunosuppressive (resemble Ly6Clow), whereas monocytes with lower CXCR4 expression have an enriched profile of genes associated with the innate response." (PMID 35053248, 2022). "miR-193-5p is known to impede the proliferation of colorectal cancer cells by inhibiting the expression of CXCR4." (PMID 35893797, 2022). "In colorectal cancer and acute myeloid leukemia, miR-9 targets and represses C-X-C Motif Chemokine Receptor 4 (CXCR4), which influences cell proliferation and the epithelial–mesenchymal transition (EMT)." (PMID 35681531, 2022). "The phenotype of CSCs and their resistance to chemotherapy drugs are related to C-X-C motif chemokine receptor 4 (CXCR4) overexpression in colorectal cancer." (PMID 35673561, 2022). "The literature reported that CXCL12/CXCR4 axis was extensively involved in the migration and invasion of colorectal cancer and other cancers." (PMID 36569343, 2022).
colorectal cancer (continued). "Colorectal cancer is among one of the highly prevalent CXCR4+ cancers in men and women, with growing incidence and worldwide spread." (PMID 34834337, 2021). "In this study, we have explored the potential of the human albumin-derived peptide, EPI-X4, as a suitable ligand to target colorectal cancer via the cell surface protein CXCR4, a chemokine receptor overexpressed in cancer stem cells." (PMID 34208189, 2021). "More and more evidence showed that the activation of CXCL12/CXCR4 axis is related to liver metastasis and poor prognosis of patients with colorectal cancer." (PMID 34930323, 2021). "Among others, these include leukemia, lymphoma, head and neck and colorectal cancer, in which CXCR4 is overexpressed in metastatic cancer stem cells." (PMID 34834337, 2021). "After transfected with CXCR4 siRNA or co-cultured with fibroblasts, colorectal cancer cells were pretreated with different concentration of CXCL12 and incubated for 24 h, and then cell invasion were performed by Matrigel assay." (PMID 34930323, 2021). "The promotion of invasive capability of colorectal cancer cells by CXCL12 were blocked by CXCR4 siRNA (*P < 0.01compared with control)." (PMID 34930323, 2021). "Among all the chemokine receptors, emerging evidences suggest that the chemokine CXC receptor 4 (CXCR4) is closely related with the development of multiple cancers, such as breast cancer, colorectal cancer, gastric cancer and adrenocortical cancer." (PMID 34180759, 2021). "C-X-C chemokine receptor type 4 (CXCR4), a G-protein-coupled receptor, has been demonstrated to stimulate proliferation and invasiveness of many different tumors, including colorectal cancer." (PMID 34209026, 2021). "Our previous studies have shown that the protection of colorectal cancer cells from radiotherapy by CXCL12/CXCR4 is mediated by survivin in colorectal cancer." (PMID 34439306, 2021). "Overexpression of high CXCR4 confers poor prognosis of oesophageal, gastric, and colorectal cancers." (PMID 34484469, 2021). "IL-Ra can inhibit the tumor-promoting effect of CXCR4/CXCL12 signal in the microenvironment of colorectal cancer by antagonizing the secretion of IL-1α in colorectal cancer cells, and then inhibit the liver metastasis of colorectal cancer." (PMID 34930323, 2021). "It has been proved that after colorectal cancer cells activate the CXCL12/CXCR4 axis, the miRNAs secreted by colorectal cancer cells can be absorbed by macrophages and transform macrophages to M2 phenotype by targeting PTEN." (PMID 34930323, 2021). "Another study discovered that in patients with colorectal cancer liver metastases, the expression of CXCR4 CXCR7, TLR2/TLR4, and PD-1/PD-L1 was significantly increased in metastatic liver tissues compared to unaffected liver tissues." (PMID 34568309, 2021). "And CXCR4 siRNA regulates the proliferation of colorectal cancer and vascular endothelial cells by inhibiting the CXCR4/CXCL12 axis." (PMID 34930323, 2021). "At this stage, to assess in detail the clinical potential of targeted NPs, in vivo biodistribution analyses were performed in a CXCR4+ subcutaneous mouse model of patient-derived M5 colorectal cancer." (PMID 34208189, 2021). "Autocrine IL-1α and paracrine CXCL12 co-enhances the metastatic potential of colorectal cancer cells; IL-1Ra can inhibit the metastatic potential of colorectal cancer cells via decrease IL-1α/CXCR4/CXCL12 signaling pathways." (PMID 34930323, 2021). "Similar results have been observed in colorectal cancer, miR-193a-5p reduces the chemotherapy resistance of colorectal cancer to 5-FU and oxaliplatin by targeting CXCR4." (PMID 34759953, 2021). "Authors performed IEF on agarose gel to demonstrate the existence of a soluble form of CXCR4 in human sera and confirmed that serum CXCR4 level was significantly elevated in cancer patients such as colorectal cancer patients compared to controls." (PMID 32867211, 2020).
colorectal cancer (continued). "The CXCL12/CXCR4 axis also activates the EMT program in colorectal cancer, targeting the Wnt/β-catenin pathway, and in multiple carcinomas such as pancreatic cancer, ovarian cancer and non-small cell lung cancer (NSCLC)." (PMID 32708431, 2020). "In colorectal cancer, the C-X-C chemokine receptor type 4 (CXCR4)/TGF-β1 axis has been described as essential for the differentiation of mesenchymal stem cells into CAFs, which in turn promote tumor growth and metastasis." (PMID 32957712, 2020). "CXCR4 belongs to a superfamily of G protein-couple receptors, and is functionally expressed in different types of cancer cells, including colorectal cancer cells." (PMID 32545884, 2020). "Since CXCR4 was reported to activate the EMT program in colorectal cancer, and chemotherapy to induce chemoresistance through the EMT program, EMT transition was evaluated as a possible Pep R mechanism of action." (PMID 32708431, 2020). "Our study showed that genes co-expressed with AGTPBP1 were associated with Nef genes of human immunodeficiency virus (HIV) and signal transduction, which antagonize the chemokine receptor CXCR4 and have an apoptotic effect on human colorectal cancer." (PMID 33276627, 2020). "Consistently, using the same approach, our group previously proved T22-PE24-H6 capacity to selective eliminate CXCR4+ colorectal cancer cells in a SC tumor model 11,16." (PMID 32373205, 2020). "In vitro assay using cell model by overexpressing and silencing of CXCR4, we unraveled that miR-133a-3p was significantly reduced in colorectal cancer cells overexpressing CXCR4." (PMID 30678736, 2019). "Taken together, these data suggest that in clinical colorectal cancer patients high CXCR4 expression contribute to CRC progression and invasion through recruiting macrophages and upregulation of RhoA by repressing miR-133a-3p." (PMID 30678736, 2019). "It has been found that the expression levels of CXCR4 correlate with the stage of the tumor, lymph node, and liver metastasis and with a higher expression in the most advanced stages of colorectal cancer." (PMID 31073530, 2019). "Liver metastasis is a very important characteristic of colorectal cancer, and it is believed that the CXCR4 expressed on the colorectal cancer cells responds to the CXCL12 released from liver which induced the directional metastasis." (PMID 31275425, 2019). "Our results highlight the important role of CXCR4 in promoting inflammation-driven colorectal cancer progression through activation of RhoA/ROCK signaling by lncRNA XIST mediated sponging of miR-133a." (PMID 30678736, 2019). "We found HQEZ decreased the expression of CXCR4 in colorectal cancer cells, and we also found the inhibition of EMT and β-catenin." (PMID 31275425, 2019). "It is thought the CXCR4/CXCL12 axis is an important factor inducing liver metastasis in colorectal cancers." (PMID 31275425, 2019). "Colorectal cancer (CRC) cells overexpressing CXCR4 display trafficking functions and metastasis‐initiating capacity." (PMID 30190334, 2018). "CXCR4 is also highly expressed in colorectal cancer, building a therapeutic rationale for CXCR4 targeting." (PMID 30319622, 2018). "Recent studies showed that chemokine CXCL12 and its receptor CXCR4 play an important role in the proliferation and organ-specific metastasis of colorectal cancer." (PMID 29305742, 2018). "CXCR4 is a specific receptor of stromal cell-derived factor 1 (SDF-1); the SDF-1 is highly expressed in the liver, which promotes the circulating CXCR4+ colorectal cancer cells to move into the liver." (PMID 30279970, 2018). "This contradictive phenomenon can be partly explained by the fact that CXCR4 expression level in liver metastases was lower than that in primary colorectal cancer tissues." (PMID 27835898, 2016). "The stromal cell–derived factor-1 (SDF-1)/CXC receptor 4 (CXCR4) axis plays an important role in tumor angiogenesis and invasiveness in colorectal cancer (CRC) progression." (PMID 27668882, 2016).
colorectal cancer (continued). "The PI3K/AKT signalling pathway also enhances CXCR4 expression in various types of tumour cells, such as hepatoma cells 47, colorectal cancer cells 48, and prostate tumour cells." (PMID 26871266, 2016). "Our findings provide evidence of the molecular mechanism by which CXCR4 mediated an anti-apoptosis pathway in chemoresistant colorectal cancer cells with OXA, suggesting that CXCR4 signaling is associated with drug resistance." (PMID 27668882, 2016). "We have here explored the nanoarchitecture and in vitro and in vivo functionalities of CXCR4-targeted, self-assembling protein nanoparticles intended for intracellular delivery of drugs and imaging agents in colorectal cancer." (PMID 27059706, 2016). "These particles are formed by a self-organizing, CXCR4-targeted polypeptide that accumulates, in the assembled form, in tumoral tissues of colorectal cancer animal models." (PMID 27059706, 2016). "Our previous studies have indicated that colorectal cancer cells express CXCR4 and that SDF-1 promotes their survival and migration to distant tissues." (PMID 27668882, 2016). "In human colorectal cancer, the expression of CXCR4 was found correlated with the recurrence and liver metastasis." (PMID 27007162, 2016). "Our results imply that CXCR4 mediated an anti-apoptosis and aggressive pathways in chemoresistant colorectal cancer cells with the OXA drug through PI3K/Akt/ERK1/2/NFκB." (PMID 27668882, 2016). "So far, numerous studies have demonstrated the expression of CXCR4 in different types of gastrointestinal neoplasia such as gastric cancer and colorectal cancer." (PMID 26091099, 2015). "CXCR4 is of particular importance in other solid cancers, including gastric cancer and colorectal cancer." (PMID 25544759, 2015). "Due to the crucial role of HIF-1α and CXCR4/CXCL12 in the metastatic process of colorectal cancer, we determined CXCR4 and CXCR7 gene expression in human colon carcinomas and their modulation by hypoxia and HIF-1α in colon cancer cell lines." (PMID 24629239, 2014). "Taken together, these results indicate the potential of targeting HIF-1α and CXCR4/CXCL12 in colorectal cancer." (PMID 24629239, 2014). "In colorectal cancer, AXL expression is associated to increased invasiveness of tumor cell lines with overexpression of the chemokine receptors CXCR4 and CXCR7, and AXL knock-down in these cell lines significantly hampered tumor cell invasion." (PMID 25193853, 2014). "Our aim was to study the significance of targeting HIF-1α and the CXCR4/CXCL12 axis in colorectal cancer to prevent the dissemination process in vitro." (PMID 24629239, 2014). "In the case of other cancers, CXCR4 has been shown to be expressed in both cytoplasm and nucleus of lung and colorectal cancers." (PMID 24659999, 2014). "Another study also proved that stromal cell-derived factor 1 (SDF-1) and its receptor, CXCR4, promoted colorectal cancer progression and EMT by activation of β-catenin." (PMID 25542041, 2014). "To further confirm that the CXCR4 protein is suppressed by miR-133b, we then overexpressed and knocked down miR-133b in colorectal cancer cell lines." (PMID 24330809, 2013). "Studies with colorectal cancers show that CXCR4 signaling is also involved in outgrowth of metastasis." (PMID 23902739, 2013). "Our group and others have examined CXCR4 expression in colorectal cancer and observed a potential role for CXCR4 in colorectal cancer progression." (PMID 22319600, 2012). "The CXC chemokine ligand 12 (CXCL12)/stromal cell-derived factor-1 (SDF-1) and CXC receptor 4 (CXCR4) axis is involved in human colorectal cancer (CRC) carcinogenesis and can promote the progression of CRC." (PMID 23098564, 2012). "CXCR4 is the most common chemokine expressed in human tumors such as breast cancer, colorectal cancer, and ovarian cancer, and SDF-1 is highly expressed at sites of metastasis including the lung, bone marrow, lymph nodes, and liver." (PMID 20953377, 2010).
colorectal cancer (continued). "We examined SDF-1α and CXCR4 expression in colorectal cancers (CRCs) and their related lymph nodes (LNs), and investigated its relationship to clinicopathological features." (PMID 18443596, 2008). "Colorectal cancer patients with nuclear CXCR4 expression showed significantly more frequent LN metastasis than did those with cytomembrane expression." (PMID 18443596, 2008). "Colorectal cancer patients with nuclear CXCR4 expression in the primary lesion frequently had cytomembrane CXCR4-positive tumours in their LNs." (PMID 18443596, 2008). "Kim and colleagues found that in patients with colorectal cancer with livermetastases, higher CXCR4 expression was found on metastatic tissues compared tothe primary tumor." (PMID 18779872, 2008). "In our experiments, immunohistochemical staining of human HCC specimens displayed cytoplasmatic CXCR4 expression with variable intensities, matching the observations made in human colorectal cancer cell lines." (PMID 16819541, 2006). "In colorectal cancer, MIF promotes the migration and invasion of tumor cells by activating the CXCR4 signaling pathway, thereby increasing the risk of tumor metastasis.We further identified the pathways involving core genes and the interaction relationships between the cells." (PMID 40110199, 2025). "Moreover, non-coding RNAs upregulate CXCR4, as seen with miR-340-5p, which promotes growth and metastasis in colorectal cancer or miR-588, which drives tumor growth in head and neck carcinoma." (PMID 40307933, 2025). "DE-specific pathways involved in Colorectal Cancer Metastasis Signaling and CXCR4 signaling suggested that short-lived RONS generated during DE treatment might trigger cellular stress responses and activate migration-related signaling pathways." (PMID 39857768, 2025). "If confirmed, the nuclear staining of CXCR4 could serve as a marker to identify metastatic colorectal cancer cells, which could have immediate applications in diagnostic immunohistochemistry." (PMID 39195225, 2024). "However, combining CXCR4 or CCR5 antagonists with anti-PD1 immunotherapy has shown promising results in clinical studies in patients with colorectal cancer and pancreatic ductal adenocarcinoma." (PMID 39001456, 2024). "This suggests that the staining intensity could represent a reliable diagnostic marker for identifying clinical outcomes related to the SDF-1 and CXCR4 expression in colorectal cancer." (PMID 39195225, 2024). "C-X-C-motif chemokine receptor 4 (CXCR4) is a crucial receptor for the chemokine stromal cell-derived factor-1 involved in the development, chemotaxis, and metastasis of various tumor types, including pancreatic, breast, lung, prostate, and colorectal cancers." (PMID 38646648, 2024). "In summary, this systematic review and meta-analysis elucidate that tumoral overexpression of CXCR4 in 1381 patients represents a promising prognostic factor, resulting in significantly shortened overall survival as well as disease-free survival in colorectal cancer patients." (PMID 38791414, 2024). "CXCL12 and its receptor CXCR4 are independent prognostic factors in colorectal cancer." (PMID 35615089, 2022). "CXCR4 was reported to be expressed in many human tumors, such as breast and colorectal cancer." (PMID 35877436, 2022). "Moreover, combining CXCR4 or CCR5 antagonists with anti-PD1 immunotherapy has shown promising results in colorectal cancer, renal cell carcinoma, and pancreatic ductal adenocarcinoma, including clinical trials." (PMID 36613922, 2022). "CXCR4 was reported to be expressed in many human tumors and has been found to be a prognostic marker in various types of cancer, including breast cancer and colorectal cancer." (PMID 35877436, 2022). "CXCR4 is also involved in chemotherapy resistance in colorectal cancer cells." (PMID 36118530, 2022).